NLRP3 (NLR family pyrin domain containing 3)
Diseases named in the same sentence as NLRP3 in open-access papers (continued):
Sharing a sentence is not in itself a finding about the gene and the disease.
Sepsis (continued). "Because inhibition of the NLRP3/IL-1β pathway slowed myocardial atrophy and cardiomyopathy in sepsis, it can prevent SCM." (PMID 37996554, 2023). "The NLRP3 inflammasome, circular RNA, and sepsis were identified as research hotspots in this field." (PMID 38013295, 2023). "In order to clarify the precise mechanisms of NR1H3 against inflammation during sepsis, we specifically focused on the inflammation‐related NLRP3 signaling pathway." (PMID 37206244, 2023). "Inhibition of NLRP3 resulted in remission of LPS‐induced cardiac dysfunction in mice with sepsis and improved survival, This suggests that the protective effect of septic cardiac dysfunction can be accomplished by inhibiting NLRP3 inflammasome." (PMID 37904696, 2023). "In summary, miR-15b-5p inhibition opposed the NLRP3 pathways related to inflammatory stress and impaired endothelium during sepsis." (PMID 37587410, 2023). "YTHDF1 alleviated sepsis by upregulating the transcription of WWP1 to induce NLRP3 ubiquitination and inhibit caspase-1-dependent pyroptosis." (PMID 38022612, 2023). "Babaodan, a natural preparation, appeared to alter NF-κB and NLRP3 (NLR family pyrin domain containing 3) inflammasome complex assembly to limit LPS-induced sepsis." (PMID 37508557, 2023). "In particular, MCC950, which inhibits NLRP3 by directly targeting the NLRP3 ATP-hydrolysis motif, attenuates multi-organ injuries in CLP rats, highlighting the potential of NLRP3 inhibitors in treating sepsis." (PMID 36756123, 2023). "Curcumin and licochalcone B inhibit the activation of the NLR family pyrin domain-containing protein 3 (NLRP3) inflammasome, thereby showing a protective effect against sepsis." (PMID 36361685, 2022). "Inhibitors of NLRP3 are being developed for a number of clinical applications including inflammatory disease, cancer, sepsis, Alzheimer’s disease, and Parkinson’s disease." (PMID 35298334, 2022). "On the other hand, NLRP3/IL-1β inflammasome pathway inhibition attenuates cardiac atrophy and cardiomyopathy in sepsis." (PMID 36359339, 2022). "It has been revealed that NLRP3‐mediated pyroptosis is capable of exacerbating inflammation in SIRS/sepsis." (PMID 35548710, 2022). "Next, we found the hyperactivation of NLRP3 inflammasome in the intestinal macrophages of Card9−/−-sepsis mice." (PMID 35618701, 2022). "In the current study, Western blot results showed that hippocampal NLRP3, procaspase-1, and cleaved caspase-1 were upregulated in the sepsis brain injury mice." (PMID 35571246, 2022). "MIF has been considered a necessary factor for NLRP3 inflammasome formation in sepsis and in systemic lupus erythematosus." (PMID 35165294, 2022). "In sepsis, the modulation of NLRP-3 activation is critical, and mefenamic acid (MFA) is a potent drug that can reduce inflammasome activity, attenuating the acute cerebral inflammatory process." (PMID 36333747, 2022). "Taken together, MIF promoted NLRP3 inflammasome mediated cell pyroptosis in sepsis-induced AKI via modulating NF-κB pathway." (PMID 35165294, 2022). "Further exploration found that 2-DG inhibited NLRP3 inflammasome activation in macrophages during sepsis." (PMID 35847986, 2022). "In conclusion, the current findings demonstrated that the activation of PPARγ reduced ROS levels and inhibited the TXNIP/NLRP3 signaling pathway to decrease pyroptosis and reduce liver damage during sepsis." (PMID 35136484, 2022). "We showed that sepsis-exo or miR-885-5p mimic not only elevated IL-1β and IL-18, but also increased NLRP3, caspase-1, and GSDMD-N, leading to promotion of pyroptosis." (PMID 35345489, 2022). "IL-1β is primarily released from the activated NLRP3 inflammasome, which plays a pivotal role in the pathogenesis of sepsis." (PMID 35178052, 2022). "Inhibitors of NLRP3 (cortistatin and sulfur dioxide) can attenuate the inflammatory response in mouse models of sepsis and thereby prevent sepsis-induced cardiac dysfunction." (PMID 35774785, 2022).
Sepsis (continued). "It has been found that pyroptosis participated in the pathogenesis of sepsis-induced myocardial injury which was associated with the XIST/miR-150-5p/c-Fos axis and ER/SIRT1/NLRP3/GSDMD pathway." (PMID 35509275, 2022). "Western blotting revealed that sepsis promoted the expression of NLRP3, IL-18, and GSDMD-N in color tissues, whereas FMT and SCFAs treatment prevented the CLP-induced expression of these proteins." (PMID 36713461, 2022). "To conclude, the regulatory role of WWP1 in sepsis was achieved through its mediation of NLRP3 inflammasomes and caspase-1-dependent pyroptosis." (PMID 35508474, 2022). "There is evidence that damaged mitochondria contribute to NACHT, LRR and PYD domains‐containing protein 3 (NLRP3) inflammasome‐related sepsis." (PMID 34991517, 2022). "Because the immune system is the very first body system to be affected by sepsis and the indispensable role played by NLRP3 inflammasome, a series of approaches have been researched to modulate it in the initiation, progression, and clinical therapy." (PMID 35222388, 2022). "The NLRP3 inflammasome not only defends against pathogen infections but also contributes to multiple inflammatory tissue damage, e.g., in sepsis, type 2 diabetes (T2D), Alzheimer’s disease, and gouty arthritis." (PMID 36311752, 2022). "Additional studies showed phosphorylated IRF3 subsequently translocated into nucleus and increased the expression of NOD-like receptor protein 3 (NLRP3), leading to the development of sepsis and sepsis-induced cardiomyopathy." (PMID 36072862, 2022). "In this study, we used western blotting and ELISA to analyze the expression of NLRP3 inflammasome-related and pyroptosis-related proteins in the colon tissues of mice with sepsis." (PMID 36713461, 2022). "Clarifying the regulatory mechanism of NLRP3 inflammasome activation through multiple signaling pathways and PTMs will help to identify more therapeutic molecules in sepsis." (PMID 35720321, 2022). "Recently, multiple studies have highlighted the crucial component of the NLR family pyrin domain containing 3 (NLRP3) inflammasome in sepsis." (PMID 35222388, 2022). "The activation of the NLRP3 inflammasome is a key component in the cardiac dysfunction and the pathophysiology of sepsis." (PMID 35296647, 2022). "Several studies have found that NLRP3 inflammatory vesicles play a key role in the development and progression of sepsis, and more studies have found inhibiting NLRP3 to be an effective treatment for sepsis." (PMID 36032662, 2022). "Taken together, we suggested Card9 acts as a negative regulation factor of NLRP3 inflammasome activation, which protects against intestinal damage during sepsis." (PMID 35618701, 2022). "Another study demonstrated the protective effects of Syneilesis palmata extract against LPS-induced endotoxin and E. coli-induced sepsis mouse models via the inhibition of NLRP3 inflammasome activation." (PMID 35073994, 2022). "Downregulated activity of NLRP3 inflammasome in response to intravenous arginine administration alleviated acute kidney injury in a mouse model of polymicrobial sepsis." (PMID 35508474, 2022). "It has been concluded that the glucose metabolism of macrophages is disturbed in sepsis, and glucose metabolism further influences the occurrence and development of sepsis by regulating NLRP3 inflammasome activation." (PMID 35847986, 2022). "We and others have previously documented a pivotal role of the NLRP3 inflammasome pathway in mediating deleterious effects in sepsis." (PMID 35178052, 2022). "In human cells, neutralization via antibodies against IL-31 and its receptor enhanced NLRP3 expression and IL-1β activation, suggesting that the inflammasome plays a role in sepsis development." (PMID 35742951, 2022). "Recent studies have found that NLRP3-mediated pyroptosis leads to the depletion of immune cells, thus aggravating organ dysfunction during sepsis." (PMID 35136484, 2022).
Sepsis (continued). "We found that fisetin induced mitophagy, which promoted clearance of sepsis‐mediated damaged mitochondria and scavenging of ROS, furthermore, blocked NLRP3 inflammasome activation of CMECs and inhibited the release of IL‐1β into CNS." (PMID 34837343, 2022). "We report here that experimental sepsis led to an overactivation of the NLRP3 complex and consequent activation of its downstream mediator caspase-1, which were significantly reduced by treatment with ICOS-Fc, thus leading to reduced systemic release of IL-1β." (PMID 36119089, 2022). "Reducing IL-1β levels through inhibition of NLRP3 in microglia was shown to improve cognitive function in sepsis." (PMID 35642838, 2022). "To confirm the therapeutic effect of 8A on NLRP3 inflammasome-related diseases, we used an LPS-induced murine endotoxemia model and found that 8A significantly increased the survival of mice with sepsis." (PMID 36379253, 2022). "Previously, spirodalesol derived from Daldinia eschscholzii was shown to inhibit NLRP3 inflammasome activation and improve sepsis." (PMID 36379253, 2022). "These suggested that inhibition of MIF alleviated NLRP3 inflammasome mediated pyroptosis in sepsis-induced AKI." (PMID 35165294, 2022). "A growing number of studies have found that ROS interacts with NLRP3 inflammasome during sepsis and regulates immune-inflammatory response." (PMID 36589684, 2022). "Here, we observed the increased expression of NLRP3 in sepsis neutrophils, compared to neutrophils in sham mice." (PMID 36068299, 2022). "Treated with MCC950 (the NLRP3 inhibitor) or Ac-YVAD-CMK (the Caspase-1 inhibitor) prevented sepsis-induced neuronal damage and cognitive deficits." (PMID 36171629, 2022). "The inflammasome component NLRP3 is upregulated in sepsis which leads to the cleavage of pro-caspase-1 to caspase-1, and subsequently maturation and release of the proinflammatory cytokine, IL-1β." (PMID 35774785, 2022). "Syringaresinol (SYR) improved cardiac function and alleviated myocardial injury in sepsis-induced cardiac dysfunction mouse via the estrogen receptor (ER)/SIRT1/NLRP3/GSDMD pathway." (PMID 35509275, 2022). "Although the role of MIF regulating NLRP3 inflammasome mediated pyroptosis in sepsis-induced AKI has been confirmed by our study, further studies will be continued in the future." (PMID 35165294, 2022). "Sepsis-exos also decreased the expression of HMBOX1 but increased the levels of NLRP3, active caspase-1, pro-caspase-1, and GSDMD-N." (PMID 35345489, 2022). "To summarize, this research indicated that the newly-discovered 4-benzene-indol derivative targets NLRP3 inflammasome signaling, which consequently alleviates sepsis-related ALI." (PMID 35222388, 2022). "Mechanistically, our study further demonstrated that WWP1 suppressed caspase-1-dependent pyroptosis by promoting NLRP3 ubiquitination in sepsis." (PMID 35508474, 2022). "Inflammasomes, especially the most studied NLRP3 inflammasomes, have been reported to be activated by sepsis-induced acute lung injury, ventilator-induced lung injury, asthma, chronic obstructive pulmonary disease, and other respiratory diseases." (PMID 35453300, 2022). "PAMP/DAMP induces activation of the NLRP3 inflammasome in macrophages and production of pro-inflammatory cytokine—IL-1B, thus promoting sepsis." (PMID 36032662, 2022). "Meanwhile, geniposide inhibits the hepatocyte apoptosis to ameliorate liver injury, and geniposide blocks the apoptosis of myocardial cells mediated by NLRP3 to ameliorate sepsis-induced myocardial dysfunction." (PMID 35630796, 2022). "Collectively, the findings of the present study demonstrated that HSF1 not only inhibited the development of ALI in sepsis but also suppressed the NLRP3 inflammasome activation and IL-1β maturation." (PMID 35720321, 2022). "Dysfunction of the NLRP3 inflammasome can lead to an increased inflammatory response in the body, thus aggravating the development of sepsis." (PMID 35720321, 2022).
Sepsis (continued). "It is currently believed that inflammasomes play critical roles in the development of sepsis, among which NLRP3 inflammasome is involved to most extent." (PMID 35847986, 2022). "Previous research manifests that NLRP3 inflammasome components are overexpressed in the white blood corpuscles of sepsis patients." (PMID 35618701, 2022). "Metabolism-related enzymes and their intermediates play vital roles in the pathogenesis of sepsis by regulating nucleotide-binding domain, leucine-rich repeat, pyrin domain-containing protein 3 (NLRP3) inflammasome activation and other mechanisms." (PMID 35847986, 2022). "In recent years, NLRP3 has been reported to be widely involved in sepsis-related immune cell death and dysfunction of multiple organs." (PMID 36405697, 2022). "GGPPS1 expression was upregulated in the sepsis-induced mice lung injury model, and the activation of autophagy and NLRP3 inflammasome was found in the lung tissue of cecal ligation and puncture (CLP)-induced sepsis mice." (PMID 36059534, 2022). "Recent studies have revealed that dramatic reprogramming of macrophage metabolism is commonly occurred in sepsis, and this dysregulation is closely related with the activation of NLRP3 inflammasome." (PMID 35847986, 2022). "Studies have reported that disruption of the connection between NF-κB and NLRP3 protected mice from sepsis-induced cardiac damage [PMID: 26,045,547]." (PMID 35266443, 2022). "Here we have surprisingly found a novel small molecule compound 4-benzene-indol derivative (1,2-diol), ameliorated LPS-induced sepsis-related ALI by inhibiting the NLRP3 inflammasome." (PMID 35222388, 2022). "In this review, we thus summarized the detail mechanism of the metabolic reprogramming process and its important role in the NLRP3 inflammasome activation of macrophages in sepsis." (PMID 35847986, 2022). "Further mechanistic studies have revealed that WHSC1 exacerbates alveolar macrophage pyroptosis in sepsis-induced ALI through the NEK7-mediated activation of the NLRP3 inflammasome." (PMID 35967871, 2022). "In conclusion, up-regulation of MIF in sepsis-induced AKI shows a renal damaged effect that aggravates NLRP3 inflammasome mediated cell pyroptosis through promoting phosphorylation of p65." (PMID 35165294, 2022). "In a caecal ligation puncture model (sepsis-induced AKI), NLRP3 deficiency and caspase-1 suppression reduced kidney injury, inflammation, and caspase-1 activation." (PMID 35204131, 2022). "In the CLP mouse model, inhibition of the NLRP3/IL-1β pathway can alleviate sepsis-induced myocardial atrophy and cardiomyopathy and has a certain effect on the prevention of sepsis-induced cardiomyopathy." (PMID 36405697, 2022). "This study demonstrated a novel mechanism of MIF regulating NLRP3 inflammasome mediated pyroptosis in sepsis-induced AKI." (PMID 35165294, 2022). "NOD-like receptor family pyrin domain-containing 3 (NLRP3) inflammasomes can stimulate the inflammation and induce immune cell apoptosis to exacerbate the development of sepsis." (PMID 35508474, 2022). "Strikingly, an increasing number of studies have unfolded the involvement of NLRP3 inflammasomes in the development of sepsis and its related diseases." (PMID 35508474, 2022). "Our results indicated that increased expression of PPARγ reduced ROS levels and inhibited the TXNIP/NLRP3 signaling pathway, resulting in decreased pyroptosis and reduced liver dysfunction during sepsis." (PMID 35136484, 2022). "Mitochondrial dysfunctions in sepsis occur by several mechanisms, leading to oxidative damage (including mitochondrial DNA (mtDNA) and stimulating NLRP3 activity." (PMID 36333747, 2022). "Conversely, upregulation of NLRP3 inflammasome activation can aggravate MOF in sepsis and increase sepsis mortality." (PMID 35847986, 2022). "We first investigated the effect of KA on LPS-induced sepsis, which is a typical model of NLRP3-driven inflammation." (PMID 36311752, 2022).
Sepsis (continued). "NLRP3 is one of the members that has been studied the most as it responds to a multitude of external stimuli, including sepsis." (PMID 35057502, 2022). "In sepsis, macrophage-derived EVs mediated acute liver injury by triggering hepatocyte pyroptosis through the NLRP3 inflammasome." (PMID 36579343, 2022). "Recently, an increasing number of studies have found that the key enzymes and metabolites of glucose metabolism in macrophages are involved in the pathogenesis of sepsis by regulating the activation of the NLRP3 inflammasome." (PMID 35847986, 2022). "Researches have shown that NLRP3 inflammasome plays a critical role in the pathogenesis of inflammatory conditions including sepsis [PMID: 31,741,197]." (PMID 35266443, 2022). "In sepsis-related studies, autophagy has been shown to participate in regulating NLRP3 inflammasome activation." (PMID 35967871, 2022). "In order to further investigate the effect of YTHDF1/WWP1/NLRP3/caspase-1 axis on sepsis, RAW264.7 cells were transfected with oe-NC/oe-YTHDF1, or sh-NC/sh-WWP1." (PMID 35508474, 2022). "LBH overexpression reduced the lung injury score, lung W/D ratio, expression of proinflammatory cytokines, and NLRP3 inflammasome activation in sepsis-induced ALI mouse model." (PMID 33553423, 2021). "This suggests that inhibition of platelet activation with Clopidogrel and the decrease in inflammatory cytokines in this sepsis model is mediated, in part, by NLRP3 mechanisms." (PMID 34638670, 2021). "When sepsis cases were separated into subgroups by genotype, carriers of the GG/GC genotypes at the NLRP3 29940G>C site exhibited significantly higher NLRP3 mRNA and TNF-α levels than carriers with the CC genotype." (PMID 34172780, 2021). "The only set shared by severe COVID-19, influenza-associated ALI/ARDS and sepsis is that comprised of TLR4, TLR7 and NLRP3." (PMID 33672738, 2021). "The mechanism of anti-inflammatory effect of CA was evaluated by detecting NLRP3 inflammasome activation in lung tissue of mice with sepsis-induced ALI after 12 h via western blot analysis." (PMID 34737695, 2021). "Collectively, GPR43 reduced mitochondrial damage to suppress NLRP3 inflammasome activity by the activation of ROS production in sepsis model." (PMID 34584017, 2021). "Multiple inflammatory diseases including sepsis-induced AKI are involved in aberrant NLRP3 inflammasome activation." (PMID 34093539, 2021). "Inhibition of NLRP3 inflammasome assembly has been shown to be protective against sepsis induced organ injury." (PMID 34638670, 2021). "Polymicrobial sepsis leads to an activation of the NLRP3 inflammasome resulting in increased conversion of inactive pro‐IL‐1ß in active IL‐1ß, which acts on cardiomyocytes via the IL‐1 receptor complex (IL‐1R1/IL‐1RAcP)." (PMID 34472725, 2021). "Estrogen protects sepsis-induced liver injury by inhibiting ROS-mediated NLRP3 activation and mitochondrial dysfunction." (PMID 34220338, 2021). "The protective impact of SESN2 in regulating NLRP3 inflammasome-dependent pyroptosis is consistent with a recent report showing that SESN2 protects the host from sepsis by suppressing prolonged activation of the NLRP3 inflammasome." (PMID 34741186, 2021). "Furthermore, functional experiments suggested that this sepsis-associated NLRP3-29940G>C polymorphism might be a gain-of-function alteration that suppresses NLRP3 expression and downstream cytokine production by altering the binding of miR-146a-5p to the 3′-UTR of NLRP3." (PMID 34172780, 2021). "We investigated if deletion of Nlrp3 inhibits sepsis‐induced cardiac atrophy and if this is accompanied by an improved diastolic and systolic cardiac function in medium‐grade sepsis after 24 h." (PMID 34472725, 2021). "NLRP3‐mediated IL‐1β activation in sepsis plays a role in in the pathogenesis of septic cardiomyopathy, leading to cardiac atrophy and decreased systolic and diastolic cardiac function." (PMID 34472725, 2021).